CLDN7 (claudin 7)
Diseases named in the same sentence as CLDN7 in open-access papers (continued):
Sharing a sentence is not in itself a finding about the gene and the disease.
melanoma (2 papers, 2021 to 2022). A malignant, usually aggressive tumor composed of atypical, neoplastic melanocytes. "Its mutations are likely involved in migration, invasion, and tumorigenicity of melanoma cells, and together with CLDN7 it has been associated to the modification of adiponectin response to lifestyle intervention in overweight/obese diabetic individuals." (PMID 34440402, 2021).
urothelial carcinoma (2 papers, 2016 to 2023). A malignant neoplasm derived from the transitional epithelium of the urinary tract (urinary bladder, ureter, urethra, or renal pelvis). "The direct impact of claudin-7 on urothelial carcinomas is controversial; however, claudin-7 appears to play an antineoplastic role in this group of tumors." (PMID 38188015, 2023). "Further studies are needed to confirm the prognostic role of claudin-7 in urothelial carcinoma patients." (PMID 38188015, 2023). "Also the study in urothelial carcinoma shows no clinicopathological correlation of claudin-7 expression." (PMID 27398181, 2016).
acinar cell carcinoma (1 paper, 2023). "Furthermore, SPT is positive for claudin-18.2and claudin-7 in a few cases, and pancreatic endocrine tumor (PET), acinar cell carcinoma(ACC), and pancreatoblastoma (PB) show strong expression of claudin-7 and a lack of claudin-5 expression." (PMID 36959784, 2023).
ameloblastoma (1 paper, 2011). The most common odontogenic tumor, arising from the epithelial component of the embryonic tooth and usually affecting the molar-ramus region of the mandible or maxilla. "In conclusion, staining for α-SMA and claudin 7 seems to be beneficial for prognostication in tongue cancer, while α-SMA staining may be beneficial in differentiating ameloblastoma from ameloblastic carcinoma." (PMID 21211041, 2011).
anaplastic cancer (1 paper, 2014). "Thus, a significantly higher expression of EpCAM and claudin-7 in the anaplastic cancer cell lines was confirmed at both the mRNA and protein levels." (PMID 24727741, 2014).
asthma (1 paper, 2021). "CLDN7 expression was elevated in the lungs of mice with asthma, and in NHBE cells treated with HDM extracts." (PMID 34574829, 2021). "Levels of the TJ protein CLDN7 were decreased in the plasma of patients with asthma." (PMID 34574829, 2021).
Astigmatism (1 paper, 2022). A type of refraction error associated with abnormal curvatures on the anterior and/or posterior surface of the cornea. "To date, the known genes and candidate genes associated with astigmatism are PDGFRA, CLDN7, ACP2, and TNFAIP8L, of which PDGFRA has been shown to increase the risk of astigmatism 1.12 times." (PMID 35885949, 2022).
Barrett esophagus (1 paper, 2023). Esophageal lesion lined with columnar metaplastic epithelium which is flat or villiform. "Another such compound, zinc, is currently in a phase 1 pilot clinical trial because it was found to increase claudin-7 expression in Barrett’s esophagus and prevent the development of esophageal adenocarcinoma." (PMID 37627123, 2023).
benign breast tumors (1 paper, 2024). "Immunohistochemical staining was performed on 92 BC tissue samples and 20 benign breast tumors to verify the expression level of CLDN-7 protein and its correlation with clinicopathological features and prognosis." (PMID 39175074, 2024).
benign pancreatic tumors (1 paper, 2023). "Additionally, claudin-5 and claudin-7 have great potential in the diagnosis and differentiation of precancerous lesions and benign pancreatic tumors." (PMID 36959784, 2023).
carcinoma of the esophagus (1 paper, 2022). "Conversely, reduced expression of CLDN1 and CLDN7 correlates with invasion and metastases in gastric epithelial cells and carcinoma of the esophagus, respectively." (PMID 36077068, 2022).
colonic adenocarcinoma (1 paper, 2011). "We attempted to analyse whether an over-expression of matriptase in the colonic adenocarcinoma cell line Caco-2 influenced the claudin-7 mRNA level." (PMID 21310043, 2011).
colorectal tumors (1 paper, 2023). "It was demonstrated that the aberrant expression of CLDN2, CLDN4, CLDN5, CLDN7, and CLDN23 are associated with the clinical value in colorectal tumors." (PMID 37799140, 2023).
cystic fibrosis (1 paper, 2023). Autosomal recessive disorder caused by pathogenic variants in the CFTR gene (cystic fibrosis transmembrane conductance regulator), which encodes a chloride and bicarbonate channel expressed in epithelial cells, and follow the diagnosis criteria. "Notably, CFTR has been reported to act as a tumor suppressor in CRC, with cystic fibrosis patients prone to elevated CRC risk, and loss of CFTR previously shown to reduce expression of CLDN7." (PMID 37542051, 2023).
diabetes (1 paper, 2024). "In the ileum, diabetes was associated with a decrease in gene expression of claudin 7 which was reversed by resistant starch." (PMID 38902253, 2024).
endometrial adenocarcinomas (1 paper, 2012). "Nevertheless, the high percentage of EC cases with MSN and CLDN7 immunoexpression, and their association with tumor grade and subtypes, suggests that these proteins might play a role in tumorigenesis of endometrial adenocarcinomas." (PMID 22272721, 2012).
enteritis (1 paper, 2024). Inflammation of the small intestine. "Nonetheless, increased secretory lineage differentiation was observed in the Cldn-7 depletion group during enteritis induction." (PMID 38654000, 2024).
gastrointestinal carcinoma (1 paper, 2020). "Consistent with METHY analysis, a pan-gastrointestinal carcinoma cluster with COAD/READ-STAD was gathered in C2, which had high level of CDH1, CLDN7 and TYRO3, and a low level of CAV1." (PMID 32874774, 2020).
glioma (1 paper, 2017). A benign or malignant brain and spinal cord tumor that arises from glial cells (astrocytes, oligodendrocytes, ependymal cells). "Thus, future studies may also be geared towards delineating the links between Daam2 and these other downregulated candidates (i.e. Claudin-7 and Syk, etc.)in the context of glioma and glial development." (PMID 29053101, 2017).
HIV-1 infection (1 paper, 2005). The type species of lentivirus and the etiologic agent of acquired immunodeficiency syndrome (AIDS). "Because many tissues of the gastrointestinal and urogenital systems express the CLDN-7 gene, the cells in these tissues may be more susceptible to HIV-1 infection." (PMID 16368003, 2005). "As described here, we found that a membrane protein, CLDN-7, can serve as a receptor for HIV-1 infection of CD4(-) cells or as a ligand on the viral envelope." (PMID 16368003, 2005). "A possible explanation for increased HIV-1 infectivity for the CLDN-7-transfected cells is that gp120-independent HIV-1 infection is mediated by an interaction between a cellular protein on the viral envelope and CLDN-7 expression on the surface of transfected 293T cells." (PMID 16368003, 2005).
Hypertension (1 paper, 2019). The presence of chronic increased pressure in the systemic arterial system. "We also found that WNK4 (its mutations lead to hypertension) expression, but not WNK1, was significantly increased in CLDN7−/− CD cell lines as well as in primary CLDN7−/− CD cells, suggesting that the expression of WNK4 was modulated by CLDN7." (PMID 31382627, 2019).
irritable bowel syndrome (1 paper, 2017). Irritable bowel syndrome (IBS) is a chronic functional condition of the lower gastrointestinal (GI) tract characterized by abdominal pain or discomfort and disordered bowel habit (diarrhea, constipation, or fluctuation between the two). "Similarly, the expression of clauidn-1, claudin-7, JAM-A, occludin, and ZO-1 in the ileal, cecal, and rectal mucosa did not change between control and diarrhea-predominant irritable bowel syndrome samples." (PMID 28366996, 2017).
Japanese encephalitis (1 paper, 2021). A disease due to a virus transmitted by an arthropod). "Importantly, Japanese encephalitis and yellow fever viruses, both closely related to ZIKV, were replicating as efficiently in control hCMEC/D3 cells than in CLDN7-KD cells." (PMID 34616388, 2021).
kidney (1 paper, 2018). "The aging of the kidney modulates the expression of various genes, e.g., the levels of mRNA of claudin-7, KIM-1, and metalloproteinase MMP-7, which are good markers associated with renal injury and various kidney pathologies." (PMID 30360430, 2018).
kidney stones (1 paper, 2024). "In this study, CLDN1 expression was found to be increased in patients with a history of recurrent kidney stones and to be highly positively correlated with CLDN4, CLDN7 and CLDN14 and moderately correlated with CLDN2 and CLDN8." (PMID 39345805, 2024).
liver cancer (1 paper, 2023). An epithelial or non-epithelial malignant neoplasm that arises from the liver.
Lupus (1 paper, 2023). "Although lesser ODs were detected for ANA, TG2, TG6, heparin, α-myosin, chondroitin sulfate, Lupus RO-60, fibrinogen, tyrosinase, β catenin, thyroid peroxidase, claudin 7, sulfatides, somatotropin, S100B, somatostatin and actin, their p values were still very, very significant." (PMID 37845267, 2023).
medullary carcinomas (1 paper, 2014). "Only one patient was positive for CLDN1, CLDN2, and CLDN7 expression, and two of three patients with medullary carcinomas were positive for CLDN4 expression." (PMID 25393310, 2014).
metastatic cancer (1 paper, 2021). A carcinoma which has spread from the original site of growth to another anatomic site. "Additionally, in previous study, Cldn7 expression was significantly lower in metastatic cancer tissues than in primary tumours, while Sox9 expression was increased in liver metastasis and lung metastasis cancer tissues." (PMID 34281572, 2021).
mucositis (1 paper, 2021). Mucositis is inflammation and damage of the mucous membranes lining the mouth and other parts of the gastrointestinal (GI) tract. "Our present studies identified a disruption of the intestinal intercellular structure and a reduced expression of ZO-1, Claudin-7, and Occludin in mice with mucositis." (PMID 34795594, 2021).
nasopharyngeal squamous cell carcinoma (1 paper, 2017). A squamous cell carcinoma that arises from the nasopharynx. "CLDN7 expression was negatively correlated with the differentiation status of the nasopharyngeal squamous cell carcinoma, with a higher expression in undifferentiated NPC samples." (PMID 28055967, 2017).
neuroblastoma (1 paper, 2023). Neuroblastoma (NB) is the most common solid, extracranial childhood tumor. "Unique to SCLC, we observed higher epithelial junction proteins (Claudin-7 and E-cadherin) in the high-NE-score lines, these epithelial markers were however not expressed in the neuroblastoma lines." (PMID 37255415, 2023).
odontogenic cyst (1 paper, 2022). A cyst in the jaw that arises from tissues of tooth development. "Every odontogenic cyst type was positive for claudin-7, but the proportion of positive cells was less than that seen for claudin-1." (PMID 34808689, 2022).
ovarian tumors (1 paper, 2011). "By western analysis, primary ovarian tumor tissues exhibited variable expression of claudin-7 ranging from moderate to high expression in 66%, low in 24%, and undetectable in 10% tumor tissue samples." (PMID 21789222, 2011). "In this report, we first evaluate claudin-7 expression levels in ovarian tissue samples and cell lines using western blotting, RT-PCR, and immunohistochemistry and find that claudin-7 is widely expressed in ovarian tumors." (PMID 21789222, 2011).
rectal tumors (1 paper, 2022). "Protein network analysis highlighted the role of the LCN2–SLC22A17–MMP9 network in TME by the interaction with fibronectin 1 and claudin 7, especially in rectal tumors." (PMID 36211450, 2022).
renal cell carcinoma (1 paper, 2019). "Claudin-7 usually shows mild-to-moderate cytoplasmic reactivity and mild and discontinuous membranous reactivity in some renal cell carcinomas, all of which should not be counted as positive staining in diagnostic practice." (PMID 31737127, 2019). "In addition, we found that Claudin-7 is usually positive in fibrotic/hyaline, edematous, or cystic regions in renal cell carcinomas, regardless of the reactivity of the tumor for Claudin-7." (PMID 31737127, 2019).
renal oncocytomas (1 paper, 2009). "Markers such as cytokeratin 7, parvalbumin or claudin 7 were found to be expressed in the majority of chromophobe RCCs, but rarely in renal oncocytomas." (PMID 19445733, 2009).
serous ovarian cancer (1 paper, 2023). "Among these, DH1, VEGFA, EPCAM, ITGB2, and CLDN7 had the highest correlation scores with serous ovarian cancer." (PMID 36980477, 2023).
sinusitis (1 paper, 2017). An acute or chronic inflammatory process affecting the mucous membranes of any sinus cavity. "CLDN-1 and CLDN-4 were downregulated in the sinusitis and NPs, whereas no change of CLDN-7 was observed in sinusitis or NPs." (PMID 28883651, 2017).
tumor (105 papers, 2005 to 2026). "Conversely, maintaining CLDN7 expression can limit tumor aggressiveness and has been associated with better response to cisplatin." (PMID 40687428, 2025). "Low or loss of CLDN7 expression was also associated with advanced stage, higher tumor grade, and positive lymph nodes." (PMID 38540693, 2024). "The 4-tier scoring method revealed association of claudin-7 expression with molecular tumor subtypes (p = 0.001)." (PMID 39687048, 2024). "The TIMER2.0 analysis revealed that the rate of immune cell infiltration into the tumor was increased in association with CLDN7 OE in BC samples than in the controls." (PMID 39175074, 2024). "In solid organoids, there was also a significant reduction in the expression of Cldn7 and Cldn4, which belong to the tight junction protein family previously associated with tumor differentiation, liver metastasis, and decreased survival in patients with PDAC." (PMID 36828915, 2023). "Nonetheless, one study found an association between low expression of claudin-7 and higher tumor grade." (PMID 38188015, 2023). "Tumor expression of CYP1B1 was inversely associated with CLDN7 expression, and CYP1B1HI/CLDN7LOW identified patients with lower median survival." (PMID 36077068, 2022). "A significant correlation (p = 0.033) was identified between Claudin-7 invasive front intensity and tumor leukocyte infiltrate, implying that a decrease in Claudin-7 intensity in the tumor invasive front is associated with an increase in leukocyte infiltrate." (PMID 35740581, 2022). "Low-level claudin 7 expression is associated with better prognosis of patients with oral squamous cell carcinoma, and in prostate carcinoma, with increased tumor grade." (PMID 29482498, 2018). "Collectively, CLDN7 was downregulated in ccRCC patients and was significantly associated with tumor progression features." (PMID 30428910, 2018). "Cytoplasmic claudin 7 expression was associated with smaller tumor size (p = 0.0053), better differentiation (p = 0.043) and with sites other than bone as the first metastatic site (p = 0.016)." (PMID 29482498, 2018). "Analysis of follow up data, clinical features and CLDN7 expression and methylation data, demonstrated that the lower expression and higher methylation status of CLDN7 were significantly associated with tumor progression and poor prognosis." (PMID 30428910, 2018). "Several studies further reported that CLDN7 had polymerization tendency and can be found outside of TJ, and that the role of CLDN7 in tumor was associated with their polymerization and localization status inside the cells." (PMID 28055967, 2017). "In contrast, tumor-associated claudin-7 was either unchanged or decreased in invasive areas in three further CRC studies." (PMID 26243458, 2016). "There is evidence that tumor-promoting EpCAM activities are modulated by the association with claudin-7." (PMID 25514462, 2015). "Analysis of the cBioPortal tumor database showed that the CLDN7 gene could be mutated, downregulated, and even deleted in BC and many other cancers." (PMID 39175074, 2024). "Nevertheless, loss of claudin-7 was associated with tumor recurrence and poor overall survival." (PMID 38188015, 2023). "Furthermore, associations between the reduced expression of claudin-7 and the stage of a tumor, or the presence of lymph node metastases, were found." (PMID 36232536, 2022). "we speculate that NPC with a high expression of CLDN7 especially the palmitoylated CLDN7 may also cause correspondent changes in MMPs to assist the tumor cells invasion, which requires further evidence to approve." (PMID 28055967, 2017). "More specifically, loss of CLDN7 was reported in breast carcinoma, oral squamous cell carcinoma and colorectal carcinoma where it was found to be associated with poor prognosis in these tumor types." (PMID 22272721, 2012). "In addition, CLDN7 is associated with the drug resistance of tumor cells." (PMID 38124743, 2023).